ANKRD30BL (ankyrin repeat domain 30B like)
Synonyms: NCRNA00164; ANKRD30BP3
Tractability: Antibody: the Human Protein Atlas places it where antibodies can reach.
Gene: Protein-coding gene on chromosome 2 (132,147,591 to 132,257,969, reverse strand). Ensembl gene ENSG00000163046.
Subcellular location (Human Protein Atlas): Plasma membrane
Genetic constraint (gnomAD): Loss-of-function variants: 7 observed, 4.75 expected, observed/expected ratio (o/e) 1.47, 90% interval 0.78 to 1.93. That is too few expected variants to judge how well the gene tolerates losing a copy. Missense variants: 76 observed, 68.06 expected, observed/expected ratio (o/e) 1.12, 90% interval 0.93 to 1.35. Synonymous variants: 21 observed, 22.96 expected, observed/expected ratio (o/e) 0.91, 90% interval 0.65 to 1.32.
Homologues: Orthologues: macaque ANKRD30BL (93% identical), zebrafish si:ch211-272n13.3 (31% identical), Drosophila melanogaster CG8679 (15% identical), Caenorhabditis elegans lem-3 (13% identical), Caenorhabditis elegans F44E5.15 (10% identical), tropical clawed frog ankrd7 (9% identical), Caenorhabditis elegans K07D4.2 (1% identical), Drosophila melanogaster CG42391 (1% identical). Paralogues in human: ANKRD30A (78% identical), ANKRD30B (73% identical), ANKRD26 (48% identical), ANKRD20A1 (43% identical), ANKRD18B (42% identical), ANKRD18A (41% identical), ANKRD62 (36% identical).
Diseases named in the same sentence as ANKRD30BL in open-access papers:
ANKRD30BL is named in the same sentence as 2 diseases in open-access papers, as found by Europe PMC text mining. Sharing a sentence is not in itself a finding about the gene and the disease. The quoted sentences say what the papers report.
neurodegenerative disease (1 paper, 2025). A disorder of the central nervous system characterized by gradual and progressive loss of neural tissue and neurologic function. "Similarly, ankyrin repeat domain 30B like (ANKRD30BL, 2q21.2), catenin alpha 3 (CTNNA3, 10q21.3), and eukaryotic translation initiation factor 4 gamma 3 (EIF4G3, 1p36.12), all previously implicated in neurodegenerative diseases, were also found to undergo sex‐specific RNA editing." (PMID 40631452, 2025).
ANKRD30BL also shares sentences with these, for which no sentence is quoted: tumor (1 paper).